OCLN (occludin)
Diseases named in the same sentence as OCLN in open-access papers (continued):
Sharing a sentence is not in itself a finding about the gene and the disease.
neurological disorders (11 papers, 2014 to 2025). "Occludin (OCLN) encodes a main component of tight junctions and is involved in several cellular functions, with dysregulation in its function leading to neurological disorders." (PMID 35625354, 2022). "Our results suggest that loss of endothelial miR-27a-3p could be a critical event contributing to loss of claudin-5 and occludin, and therefore barrier dysfunction in neurological diseases, and restoring its expression could be a potential therapeutic strategy to preserve the barrier integrity." (PMID 35025943, 2022). "Tight junction proteins such as ZO-1, occludin and claudin-5 have been shown to be reduced in experimental neurological disease models, which consequently compromised the integrity of the BBB." (PMID 26952102, 2016). "In man, mutations of the occludin gene cause band-like calcification with simplified gyration and polymicrogyria (BLC-PMG), a rare neurological disorder resulting in malformations of cortical development, implicating a role of occludin for TJs at the BBB." (PMID 25520612, 2014). "Therefore, targeting KLF2/occludin axis mediated brain endothelial permeability might be an effective method for the treatment of T2DM-induced neurological disorders." (PMID 34266350, 2021). "We examined Claudin 1, Claudin 3, Claudin 5, Occludin and ZO-1 in 31 ALS-CP samples compared to 15 non-neurologic disease controls." (PMID 32586411, 2020). "Occludin is a key tight junction protein and serum occludin level can be a surrogate biomarker for intestinal permeability and gut disorders as well as BBB disruption in neurological disorders." (PMID 37940864, 2023). "Our findings confirm how the expression level of occludin may be indicative of BBB integrity, which may lead to new treatments for neurological disorders that target occludin." (PMID 36806348, 2023).
intestinal diseases (9 papers, 2017 to 2025). "Knockdown of occludin results in increased permeability, and the downregulation of occludin has been implicated in intestinal diseases." (PMID 36264979, 2022). "Knockdown of cccludin results in an increase of permeability and the down-regulation of occludin was implicated in intestinal diseases." (PMID 28854971, 2017). "In intestinal diseases such as UC, the barrier function is compromised, with decreased expression of tight junction proteins (e.g., ZO-1, occludin, claudin-1), leading to increased intestinal epithelial permeability." (PMID 39940311, 2025). "Obese and diabetic mice model ob/ob mice display enhanced intestinal permeability by reducing ZO-1 and occludin expression, which participates in the occurrence of intestinal disorders." (PMID 34831451, 2021). "However, limited research has explored the use of plasma occludin as a marker for intestinal diseases." (PMID 37745643, 2023). "Therefore, the levels of occludin and ZO-1 are widely considered effective targets for treatment of intestinal diseases." (PMID 36356098, 2022).
adenocarcinoma (8 papers, 2015 to 2025). A common cancer characterized by the presence of malignant glandular cells. "Both Occludin and ZO-1 exhibited decreased expression in undifferentiated adenocarcinomas of the human digestive tract." (PMID 38472174, 2024). "Studies have shown that the protein expressions of ZO-1 and occludin are reduced in adenocarcinoma of the digestive tract and that the intestinal barrier is impaired, followed by increased intestinal permeability." (PMID 34531745, 2021). "In HPAC, a cell line derived from moderately differentiated adenocarcinoma, tricellulin immunoreactivity was basically observed along the intercellular boundary just like a TJ marker protein, occludin, and was especially concentrated at a tricellular TJ, as its name means." (PMID 27641742, 2016). "Moreover, overexpression of epithelial markers (Cadherin1, Epcam and Occludin) was observed in adenocarcinoma regions." (PMID 26059540, 2015). "Heatmap analysis revealed upregulated VIM and PLK1 mRNA expression in TGF-β-treated adenocarcinoma when the mesenchymal markers CDH2, SNAI1, and SNAI2 were high and either CDH1 or OCLN (epithelial markers) was low in majority of LUAD cells analysed." (PMID 33963314, 2021).
metabolic disorders (5 papers, 2009 to 2025). "Meanwhile, it has been reported that CUR could restore tight junction protein expression, including ZO-1 and occludin, and enhance intestinal barrier integrity in metabolic disease." (PMID 39787157, 2025).
cardiovascular diseases (3 papers, 2014 to 2025). "There is evidence that occludin is related to gastro-intestinal diseases and cardiovascular diseases." (PMID 24884662, 2014). "We tested the activity of the AMPK/mTOR signalling pathway, which is a potential target pathway of resistin in cardiovascular diseases, to further determine the molecular mechanism of H. parasuis-induced resistin in regulating claudin-5 and occludin expressions in PAECs." (PMID 36694280, 2023).
cerebral artery (3 papers, 2022 to 2024). "The downregulation of the tight junction proteins ZO-1, Occludin, and Claudin-1 can lead to the destruction of tight junction structures and an increase in cell bypass permeability, leading to LPS translocation to the liver and blood circulatory system and liver inflammation and injury." (PMID 37836761, 2023). "In a mouse model of middle cerebral artery occlusion, inhibition of MMP-9 expression resulted in increased ZO-1 and occludin expression and reduced BBB permeability." (PMID 39300102, 2024).
gastrointestinal disorders (3 papers, 2020 to 2024). "Studies have linked the decreased expressions of Claudin-1, Occludin, and ZO-1 with gastrointestinal disorders where the intestinal barrier is compromised." (PMID 38516705, 2024).
brain diseases (2 papers, 2020 to 2021). "Its levels in the serum of individuals with brain disorders are significantly greater than those healthy, suggesting that occludin might be utilized as a biomarker to evaluate the risk of brain disorders and BBB dysfunction." (PMID 34912450, 2021).
retinopathy (2 papers, 2016). "In diabetic mice suffering from retinopathy, cellular tight junctions were damaged as demonstrated by the low levels of occludin detected in retinal homogenates." (PMID 26949291, 2016). "Occludin progressively decreased in the retina of mice developing retinopathy." (PMID 26949291, 2016).
vasculopathy (1 paper, 2022). "A hallmark of CAA vasculopathy is BBB hyperpermeability with altered expression of major TJ proteins, claudin-5, ZO-1, claudin-1, and occludin." (PMID 35813502, 2022).
OCLN also shares sentences with these, for which no sentence is quoted: chronic rhinosinusitis (4 papers); lung diseases (4); adenoma (3); polymicrogyria (3); acute kidney injury (2); alcohol (2); atrial fibrillation (2); coronary heart disease (2); enterocolitis (2); experimental autoimmune encephalomyelitis (2); gastrointestinal tumors (2); ileitis (2); infectious disease (2); kidney damage (2); myocardial infarct (2); pancreatic cancer (2); salmonellosis (2); serous ovarian cancer (2); vascular dementia (2); abscesses (1); acute lung injury (1); anaplastic astrocytoma (1); autism spectrum disorder (1); bipolar disorder (1); bladder urothelial carcinoma (1); bone metastasis (1); Brain atrophy (1); brain cancer (1); brain inflammation (1); breast tumor (1).
A further 68 diseases each share a sentence with OCLN in 1 paper.